IL1B (interleukin 1 beta)
Diseases named in the same sentence as IL1B in open-access papers (continued):
Sharing a sentence is not in itself a finding about the gene and the disease.
fungal infections (continued). "Moreover, ethanol consumption was able to down modulate IL-1β and IL-10 levels after fungal infection." (PMID 32701055, 2020). "Lichochalcone-A was found to significantly decrease the expression of pro-inflammatory cytokines IL-1α and IL-1β, suggesting it may have a modulatory role on the host pro-inflammatory response to help eradicate fungal infections." (PMID 27284694, 2016). "CARD9 upregulates IL-1β production in fungal infections, but whether there is a direct link between this protein and canonical inflammasome activity is unclear." (PMID 27670879, 2016). "IL-1β is primarily produced by innate immune cells such as monocytes, macrophages and dendritic cells upon activation, and is also an important cytokine for the control of fungal infection." (PMID 27434108, 2016). "In addition, priming with LPS (100 ng/ml for 2 h) before the fungal infection only poorly induced IL-1β production." (PMID 24340123, 2013). "Finally, our work provides evidence for the protective role of IL-1β during fungal infection of murine macrophages." (PMID 24340123, 2013). "Thus, the marked impact of Malt1 inhibition on IL-1β and IL-23p19 expression in response to fungal infections translates to a block in TH-17 immunity." (PMID 21283787, 2011). "From our studies, it can be inferred that initial production of IL-1β may induce IL-17A and CAMP production which can in turn positively regulate further production of IL-1β to create an inflammatory environment which limits fungal infection." (PMID 22174673, 2011). "Nevertheless, as in mammals, it is possible that the IL-1-β, IL-6 and IL-15-like proteins may play an important role in fungal infection, as their levels increased in infected insects; however, a better understanding of the role of these proteins during infection is needed." (PMID 38774871, 2024). "The significance of hub genes, specifically IL-1B, MMP9, and S100 family members, in promoting inflammatory and immunological responses during fungal infections is highlighted by this investigation." (PMID 40521031, 2025). "In the presence of IL-1β and TGF-β, IL-6 leads to polarization towards the Th17 subset, which is involved in immune defense against extracellular bacterial and fungal infections." (PMID 37018291, 2023). "There were significant differences in IL-4, IL-6, IL-8, IL-10, IL-12p70, IL-1β, IL-2, TNF-β, IL-17, and IL-22 between the uninfected group and the pulmonary bacterial and fungal infection group (P < 0.05)." (PMID 36319826, 2022). "During fungal infection, the NLRP3 inflammasome formation in immune cells leads to the activation of CASP1, which then cleaves the proinflammatory cytokines IL-1β and IL-18 to their bioactive forms and induces pyroptosis." (PMID 35463001, 2022). "During fungal infection, the activation of the NLRP3-ASC-CASP1 inflammasome leads to cleavage of pro-CASP1, which then processes the proinflammatory cytokines IL-1β and IL-18 to their bioactive forms and cleaves GSDMD to trigger pyroptosis." (PMID 35463001, 2022). "Patients with RVVC showed higher levels of IL-1β and IL-6 in CVL than Control individuals and higher IL-6 levels than patients with the acute form of the mycosis." (PMID 35049960, 2021). "Importantly, genetic variation in PFKFB3 is correlated with differential production of IL-1β after fungal infection, suggesting the existence of bidirectional signaling events, in which PFKFB3 may also be able to regulate the activation of the NLRP3 inflammasome to drive the production of IL-1β." (PMID 34044589, 2021). "The expression of mRNAs for Interleukin-1β (IL-1β), TNFα, and TLR4 were evaluated in the corneas of the mice with fungal infection and the control corneas by real-time PCR." (PMID 31285488, 2019). "IL-1β and TNF are major pro-inflammatory cytokines that are rapidly released after tissue injury and fungal infection, so we determined their expression levels in the colons of mice challenged with C. albicans and treated with DSS." (PMID 28289440, 2017).
fungal infections (continued). "With respect to inflammasome activation upon fungal infections, only the inflammasome receptors AIM2, NLRC4 and, mainly, NLRP3, are related to engaging and triggering IL-1β caspase-dependent cleavage." (PMID 29209318, 2017). "This suggests that the corneal epithelial cells can express more IL-1β, IL-6, IL-8 and CXCL1 after identifying the fungus, which resist the fungal infection and induce inflammatory cells infiltration to remove pathogenic fungi." (PMID 26036769, 2015). "Regarding fungal infections, the NLRP3 inflammasome is essential for casapase-1 activity and subsequent IL-1β release in murine and human phagocytes that are infected with C. albicans, A. fumigatus, T. schoenleinii and C. neoformans." (PMID 24340123, 2013). "In addition, our data show that NLRP3 inflammasome activation as well as pro-IL-1β expression relies on the Syk tyrosine kinase, which is downstream from the pathogen recognition receptor Dectin-1, reinforcing the importance of Dectin-1 in the innate immune response against fungal infection." (PMID 20368800, 2010). "To investigate CIN’s immunomodulatory mechanism, we analyzed Dectin-1 signaling components (Dectin-1, SYK, and CARD9), NF-κB activation, and proinflammatory cytokines (TNF-α and IL-1β) in RAW264.7 and PMA-differentiated THP-1 macrophages during a 24-h fungal infection." (PMID 41031111, 2025). "SYK controls both pro-IL-1β synthesis and NLRP3 activation in response to fungal infection." (PMID 38992615, 2024). "Th17 cells play an important role in the host defense against fungal infections, such as candidiasis, by stimulating the production of other cytokines, such as TNF-α, IL-6, and IL-1β, and enhancing the recruitment and activation of neutrophils, which are essential for killing Candida cells." (PMID 38003833, 2023). "Induction of MDSCs in fungal infections was further observed to be dependent on pathways downstream of dectin-1/CARD9 signaling, notably generation of reactive oxygen species (ROS), caspase-8 activity, and IL-1β production." (PMID 36776848, 2023). "In addition, the mRNA expression of IL-1β, TNFα and TLR4 was significantly increased in the corneas with fungal infection, compared with the control group in which only DMSO injection was administrated (P < 0.05)." (PMID 31285488, 2019). "Followed by priming, the proteolytic cleavage of pro-IL-1β into its mature form is canonically performed by the protease caspase-1, and this process is largely dependent on the assembly of the NLRP3 inflammasome in fungal infections." (PMID 29209318, 2017). "We found that FK506 may reduce the infiltration of inflammatory cells by suppressing the expression of proinflammatory cytokines such as TNFα and IL-1β and downregulating the expression of TREM-1 at an early stage of fungal infection in corneas." (PMID 25464008, 2014). "As expected, the fungal infection alone did not induce significant IL-1β production, unless ATP treatment was performed." (PMID 24340123, 2013). "Moreover, western blot analysis revealed dramatically decreased levels of pyroptosis-associated proteins ASC, cleaved CASP1, GSDMD, cleaved GSDMD, cleaved IL-1β and cleaved IL-18 in the Ad-NLRP3-shRNA group compared with the Ad-GFP-shRNA group during fungal infection." (PMID 35463001, 2022). "The absence of Gal-3, in fungal infection, a positively modulated gene involved in phagocytosis (sftpd) and negatively genes involved in signal transduction (syk and myd88), proinflammatory cytokines il-1β and il-12b and cd209a receptor." (PMID 34203011, 2021). "Additionally, M1‐type cytokines, such as IL‐4, IL‐12, IL‐6, IL‐23, TNF‐α, IL‐1β, and IFN‐β, were slightly elevated upon stimulation by fungi, but no statistical difference was detected between the two fungal infection groups." (PMID 37211685, 2023).
fungal infections (continued). "Although limited in vitro studies using NLRC4 deficient macrophages or dendritic cells challenged with Candida albicans revealed no defects in caspase-1-dependent IL-1β responses, the role of NLRC4 in live fungal infection models has not been thoroughly defined." (PMID 22174673, 2011). "Even in the absence of CD28 co-stimulation, IL-1β potently drives the differentiation into IL-17/IFN-γ double-producing T-cells (Th17) suggesting that IL-1β inducing adjuvants may foster vaccine immunogenicity against pathogens that require Th17 responses, such as pneumococcal or fungal infections." (PMID 32971761, 2020).
emphysema (66 papers, 2005 to 2025). "The association between IL-1β and emphysema was modified by smoking (p-interaction=0.020) with a more pronounced association in never-smokers (aOR: 4.53 [95%CI: 2.05-9.98], p<0.001)." (PMID 33936110, 2021). "Elevated TNFα (adjusted odds ratio (aOR): 1.89 [95%CI: 1.26-2.83], p=0.002) and IL-1β (aOR: 1.72 [95%CI: 1.14-2.59], p=0.009) were associated with emphysema in base models with adjustment for age and sex only." (PMID 33936110, 2021). "In correlation analyses, we found evidence of a weak correlation between the two inflammatory markers significantly associated with emphysema, TNFα and IL-1β (rho=0.13, p<0.001)." (PMID 33936110, 2021). "Further, we found a strong association between elevated TNFα and IL-1β with emphysema in models adjusted for age and sex." (PMID 33936110, 2021). "Elevated IL-1β levels are known to cause pulmonary inflammation as observed in emphysema and airway remodeling in mice." (PMID 31836726, 2019). "IL-1β stimulates alveolar macrophages activation, and promotes MMPs expression, causing airway destruction and emphysema." (PMID 29483875, 2018). "Overexpression of IL-1β in lung caused lung inflammation, emphysema, mucus metaplasia, and airway fibrosis in mice." (PMID 23533311, 2013). "Alternatively, as a high dose of IL-1β can cause pulmonary inflammation, emphysema, and airway remodeling in the adult murine lung or side effects like ruffled fur and reduced activity, it is possible that the increased pathology seen in our pigs was due to a different effect of IL-1β." (PMID 37153548, 2023). "Chronic expression of IL-1β causes lung inflammation and emphysema by activating lung macrophages." (PMID 35159179, 2022). "Of note, IL-1β was the only cytokine associated with visual emphysema, suggesting that IL-1β may be a more clinically relevant biomarker than TNFα." (PMID 33936110, 2021). "Two markers of systemic inflammation, TNFα and IL-1β, were independently associated with emphysema in PLWH and may contribute to the pathogenesis of emphysema." (PMID 33936110, 2021). "In a logistic regression model adjusted for age, sex, ethnicity, smoking status, BMI and CD4 nadir, elevated TNFα (adjusted odds ratio (aOR): 1.78 [95%CI: 1.14-2.76], p=0.011) and IL-1β (aOR: 1.81 [95%CI: 1.16-2.81], p=0.009) were independently associated with emphysema." (PMID 33936110, 2021). "Moreover, in interaction analyses, we found the association between IL-1β and emphysema to be modified by smoking, with a more pronounced association in never-smokers, suggesting a pathogenesis independent of excessive smoking." (PMID 33936110, 2021). "Thus, the observed association between elevated peripheral TNFα and IL-1β with emphysema, may be a consequence of a spill-over of cytokines from the affected lung tissue, where the cytokines are most active, and into the systemic circulation." (PMID 33936110, 2021). "Reduced osteoclast numbers, lower RANKL expression, and decreased expression of IL-1β and IL-6, protecting against emphysema in KO mice." (PMID 40248692, 2025). "TNF-α and IL-1β have been identified as pivotal cytokines with prominent roles in airway remodeling and the development of emphysema, capable of initiating inflammatory cascades during COPD exacerbations." (PMID 41377050, 2025). "Biologics targeting upstream alarmins (e.g., IL-33/TSLP) and downstream cytokines (e.g., IL-1β, IL-6) aim to disrupt inflammatory redundancy; cell-based and regenerative approaches represent long-term precision strategies for emphysema." (PMID 41024111, 2025). "Research indicates that myrcophenostatin protects against COPD-associated inflammation and emphysema by regulating genes for pro-inflammatory mediators like TNF-α, IL-1β, G-CSF, and KC." (PMID 39950029, 2025). "In GSE1122, IL-1β and IL-23 were significantly upregulated in the emphysema group, while IL-17 was also upregulated, and the p-value was close to 0.05 (p=0.0547)." (PMID 36248880, 2022).
emphysema (continued). "In the present study, we found an independent association between two markers of systemic inflammation, TNFα and IL-1β, and radiographic emphysema in PLWH." (PMID 33936110, 2021). "The level of secretion of IL-1β induced by CS extract and DEPs was higher in the elastin-induced emphysema than normal samples." (PMID 34574829, 2021). "CS extract and DEPs increased the secretion of IL-1β in lung tissue, from both normal and elastase-induced emphysema samples." (PMID 34574829, 2021). "Alternatively, the association between elevated TNFα and IL-1β and emphysema could reflect an upregulation of systemic inflammation which, in turn, could enhance inflammation in the lungs and accelerate the destruction of lung parenchyma and lead to emphysema in PLWH." (PMID 33936110, 2021). "We found a statistically significant interaction between elevated IL-1β and smoking status on their effect on the odds for emphysema (p-interaction=0.020)." (PMID 33936110, 2021). "Another study showed that levels of TNF-α, IL-6, and IL-1β increased in sputum during emphysema in humans." (PMID 32963734, 2020). "In different COPD models, many studies have demonstrated that IL-1β significantly contributes to airway inflammation and emphysema, where both stabile and exacerbating COPD IL-1β secretion is increased." (PMID 31601004, 2019). "Our group has demonstrated that the bronchial epithelium secretes IL-1β in response to cigarette smoke leading to lung inflammation, emphysema, fibrosis, and goblet cell hyperplasia in mice." (PMID 30380761, 2018). "Tumor necrose factor (TNF) –α, interferon-γ and various classes of interleukins as the IL-1β, IL-6, IL-8, IL-10, IL-17, IL-18, IL-32 and others are involved in the progression of emphysema." (PMID 27775634, 2016). "Specifically, we found that inhaled nCB induces the production of IL-1β and IL-6, two pro-inflammatory cytokines that are required for mDC-mediated differentiation of Th17 cells and emphysema development." (PMID 26437452, 2015). "The implication of IL-1β was also confirmed in an animal model, showing that cigarette smoke-induced emphysema was reduced in mice that were null for the receptors of IL-1β and TNF-α." (PMID 23300722, 2012). "This may be associated with the granulocytosis discussed further below but may also relate to increased expression of proinflammatory cytokines Il1b and Cxcl1, and the emphysema-like pathology that develops in these animals." (PMID 39869647, 2025). "Moreover, LincR-PPP2R5C was found to regulate the ubiquitination of IL-1β in macrophages and promote airway inflammation and emphysema in a COPD mouse model." (PMID 40413536, 2025). "Cytokine IL-1β has been shown to exert airway inflammation and emphysema in the COPD mice model." (PMID 35584087, 2022). "In conclusion, we found an independent relationship between TNFα and IL-1β and radiographic emphysema in PLWH, suggesting that systemic inflammation may be involved in the pathogenesis of emphysema." (PMID 33936110, 2021). "To examine whether the emphysema-protective effect of PRMT6 was associated with an anti-inflammatory effect on the mice after CSE injection, we measured the levels of TNFα and IL-1β in the lung tissues." (PMID 32047419, 2020). "In this study, the NLRP3 inflammasome also played an important part in PM-induced emphysema and airway inflammation in vivo and in vitro with the results that the IL-1β expression, NLRP3, and active caspase-1 (p20) was enhanced in mice and A549 cells after PM exposure." (PMID 32116706, 2020). "Chronic inflammation in pulmonary emphysema is associated with an increase in different proinflammatory mediators, including TNF-α, IL-1β, IL-6, IL-12, IL-18 and chemokines such as IL-8, MIP-2, IFN-γ, MCP-1, MIP-1β, produced mainly by neutrophils and macrophages in the lung." (PMID 29515461, 2018).